ATG5 (autophagy related 5)
Diseases named in the same sentence as ATG5 in open-access papers (continued):
Sharing a sentence is not in itself a finding about the gene and the disease.
cancer (232 papers, 2011 to 2026). A tumor composed of atypical neoplastic, often pleomorphic cells that invade other tissues. "Autophagy-related protein 5 (ATG5) has been linked with the progression of several cancers including KIRC." (PMID 35096203, 2022). "Survival analysis revealed that ATG5 was universally associated with the prognosis of pan-cancer, and high ATG5 expression was significantly associated with poor patient prognosis in most cases." (PMID 33842365, 2021). "In multiple cancer types, ATG5 mutations and alternative mRNA splicing disrupt the ATG16L1-binding to ATG5 and impair the ATG12-ATG5 conjugation." (PMID 34706732, 2021). "The ER stress inducers caused cancer cell death in an Atg5-dependent manner, in accordance with our results." (PMID 34443626, 2021). "Though the role of ATG5 is like a double-edged sword in cancer development and progression, the ATG5 knockout causes benign tumors in aged mice (19 month)." (PMID 33926066, 2021). "Deregulating autophagy by the frameshift mutations of Atg2B, Atg5, Atg9B and Atg12 is involved in cancer development." (PMID 34829743, 2021). "Neu2 overexpression causes desialylation of ɑ2,6- and ɑ2,3-linked SAs that are present on Atg5 protein in these cancer cells." (PMID 33526785, 2021). "Autophagy-related gene 5 (ATG5) is identified as an essential autophagy gene, contributing to the malignant phenotype of cancer cells, and its higher expression is closely associated with poor prognosis in patients with early-stage ESCC." (PMID 32974198, 2020). "Pancreas specific deletion of Atg5 or Atg7 hindered cancer development in GEMMs harboring one oncogenic Kras allele, the most frequent mutation in PC." (PMID 32344698, 2020). "Atg5-deficiency, Atg7-deficiency, and Beclin-1 partial deletion can spur spontaneous tumor growth commonly seen in most cancers." (PMID 29988591, 2018). "A high level of ATG5 expression in normal tissue is, even more so than in cancer tissue, significantly associated with an adverse clinical outcome in early-stage ESCC." (PMID 29207660, 2017). "Selective inhibition of autophagy, by silencing BECN1 or ATG5 in hypoxic cancer cells, restored the susceptibility to NK-mediated lysis." (PMID 27917371, 2016). "It is clarified that knock down of Atg5 or Atg7 causes impairment of autophagy system associated with apoptosis of cancer cells and inhibition of cell growth." (PMID 24725767, 2014). "Furthermore, the deletion of Atg5 or Atg7 in the pancreas in the presence of a triggering KRAS mutation prevented premalignant damage from progressing to cancer." (PMID 35740481, 2022). "The higher expression of ATG5 was also associated with poor clinical outcomes of other cancers." (PMID 34901004, 2021). "A study investigated this question by studying loss of ATG5 in RAS-driven cancer cells." (PMID 31671556, 2019). "Our observation that cancer cells that have lost the expression of Atg5 may undergo deficient or inefficient autophagy in response to cytotoxic insults has important clinical implications." (PMID 26416459, 2015). "Furthermore, the detrimental effects of Atg5 knockout on RAS-expressing cells under amino acid deprivation suggest that cancers harboring oncogenic Ras mutations are especially susceptible to the inhibition of autophagy and/or macropinocytosis (Data not shown)." (PMID 26575954, 2015). "Interestingly both agents could kill Atg5-deficient MEFs, though at a relatively lower rate, compared to the rate for some of the cancer cells." (PMID 25894744, 2015). "The association between cancer and increases in CASP3, CASP8, and ATG12/ATG5/ATG16L1 is described in the sections titled “Apoptosis”, “Exocytosis”, and “Autophagy”, respectively." (PMID 41154660, 2025). "Initial steps include analytical validation of a serum assay panel (p-cresol, S1P, 7-HOCA, DLST, MSR1, PGAM2, and ATG5) as well as known hallmarks of cancer proteins with standardized pre-analytics and central IDH and MGMT testing." (PMID 41294712, 2025).
cancer (continued). "Ceramide can trigger autophagic cell death in cancer cells by modulating the activity of autophagy-related proteins such as Beclin-1 and Atg5." (PMID 40226357, 2025). "Treatment with procaine led to increased transformation of LC3-II and increased expression of autophagy proteins Beclin-1 and ATG5, which in turn triggered apoptosis and autophagy and inhibited the proliferation and differentiation of cancer cells." (PMID 38482052, 2024). "For instance, using a CRISPR-Cas9 to generate ATG5 KO ovarian cancer stem cells have led to clarification of the pivotal role of autophagy in cancer stem cells maintenance." (PMID 39075259, 2024). "Some autophagy-related genes (ATGs), such as ATG2B, ATG5, ATG9B, and ATG12, have been reported to contain frameshift mutations in cancer, implicating the potential contributions to tumorigenesis and cancer metastasis." (PMID 38338839, 2024). "In both the control and cancer patients, there were positive correlations (p < 0.0001) between KRAS mutational status and the expression of MAP1LC3B, ATG5, ATG10, ATG13, and ATG14." (PMID 39057088, 2024). "During cancer radiation therapy, cancer cells that are resistant to glutamine depletion can induce autophagy through activating ATG5 to defend against radiation-induced damage." (PMID 38575922, 2024). "In one study, reducingautophagy with siRNAs that targeted Beclin-1or ATG-5 improved cancer immunotherapy as shown by a recovery in thesensitivity of hypoxic tumor cells to Cytolytic T lymphocytes (CTL)-mediatedlysis." (PMID 38973850, 2024). "Out of 90 cancer cases, 55 showed positive Beclin-1 staining (61.1%) and 52 showed positive Atg5 staining (57.8%)." (PMID 39650649, 2024). "In this work, improved expression of LC3 and Atg5 genes in the treatment process confirmed the beginning of the autophagy pathway in HT-29 cancer cells." (PMID 38952771, 2024). "LC3, SQSTM1 and ATG5 in cancer tissues are closely related to cancer aggressiveness and prognosis, and are often used as independent prognostic markers for cancer." (PMID 37776538, 2024). "SIRT-1, which is typically localized to the nucleus in cancer cells, forms a molecular complex with three proteins essential for autophagy initiation: ATG-5, ATG-7, and LC3." (PMID 37850626, 2023). "Namely, we observed that ATG5 silencing leads to elevated accumulation of LDs in cancer cells grown in nutrient-rich media in the presence of serum and in serum-free media." (PMID 37835551, 2023). "To confirm the role of autophagy in the anti-cancer activity of Cu E, we used lentiviral transfection of shRNA to knock down the ATG5 gene, which is a key protein involved in isolation membrane expansion and essential for autophagosome formation in A549 cells." (PMID 37886957, 2023). "Suppressing autophagy by deleting ATG5 or ATG7 will prevent malignant tumor formation and slow the development of the tumor." (PMID 37108476, 2023). "In triple-negative breast cancer (TNBC), ATG2B and ATG5 act as suppressors of cancer stemness through the induction of autophagy." (PMID 38067169, 2023). "Knockout or knockdown of ATG7 and ATG5 upregulated ferritin expression, decreased Fe2+ levels, and limited erastin-induced ferroptosis in fibroblasts and cancer cells." (PMID 37522124, 2023). "In a model of lung cancer, knockdown of ATG5, BECN1, ATG7 and p62/SQSTM1 decreases A549 cell invasiveness in the presence of cancer-associated fibroblasts (CAFs)." (PMID 37887330, 2023). "Inhibition of autophagy via late-stage autophagy inhibitors, or by knocking down autophagy-related 5 (ATG5), reduced LD accumulation in amino acid-starved cancer cells, suggesting that autophagy contributes to LD biogenesis." (PMID 37835551, 2023). "ATG5 have the ability to regulate the components of the extrinsic apoptosis and the knockdown of ATG5 was reported to protect cancer cells from apoptosis." (PMID 37174512, 2023).
cancer (continued). "Gene silencing of autophagy proteins including Beclin1, ATG5, and others inhibited autophagy and sensitized drug-resistant cancer cells." (PMID 37761021, 2023). "Autophagy inhibition by ATG3 or ATG5 depletion promotes EMT in several Ras-mutant cancer cells, indicated by the increase of EMT markers like ZEB1, ZEB2 and SNAI2; meanwhile facilitating cell migration and invasion." (PMID 37355631, 2023). "CRISPR Cas9 invalidation of Optn or Atg5 gene in cancer cells impedes the capacity of the treatment to trigger CXCL10 production by cancer, the recruitment of CD8 T cells and the therapeutic effect of the association." (PMID 35529902, 2022). "Its exosome-packed gain-of-function enhances apoptosis and reduces autophagy, re-sensitizing cells to TRA, both in vivo and in vitro models, in part by targeting autophagy-related 5 (ATG5) gene, strongly associated with cancer initiation." (PMID 34524579, 2022). "ATG5 rs510432 SNP have been shown to influence certain diseases of the immune system, cancer and neurodegenerative diseases." (PMID 34661876, 2022). "m6A modification can control cancer metabolism by modulating autophagy by targeting ATG5/7 and regulating pentose phosphate flux by promoting 6PGD translation 27,28." (PMID 35399719, 2022). "ATG5/12 and Beclin 1 overexpression in cancer cells promoted LC3-II expression and inhibited p62 accumulation, indicating upregulation of autophagic flux." (PMID 35449123, 2022). "To this end, we found that while SRC inhibitors promote cell death in cancer cells harboring oncogenic SRC, simultaneous inhibition of autophagy (by hydroxychloroquine or by ATG5 or ATG7 knockout) promotes apoptosis of cancer cells even further." (PMID 35647611, 2022). "One previous study showed that inhibiting upstream autophagy using 3-methyladenine (3MA) or Atg5 inhibition impaired the chemotherapeutic effect of IM in a range of cancer cell lines." (PMID 36233113, 2022). "It reported that knockout of ATG12 sensitizes cancer cells to CTLs, whereas knockout of ATG5 or ATG16L1 together with ATG12 results in resistance of cancer cells to CTLs." (PMID 36230955, 2022). "A single copy Atg5 deletion with the autophagy suppressor chloroquine (CQ) caused increased aggressiveness and metastatic expansion, with significant diagnostic consequences since CQ may increase the risk of creating resistant cancer cells, enhancing its aggressiveness." (PMID 35740481, 2022). "In different cell types, including glioblastoma cells or cancer associated fibroblasts (CAFs), HMGB1 secretion was dependent on the lipidation machinery components such as ATG5." (PMID 36601581, 2022). "As miR-30a is already well known to regulate autophagy through targeting BECLIN1 or ATG5, mostly in cancer cells, we chose to focus on putative targets that were more specifically involved in mitophagy." (PMID 35269458, 2022). "As reported by others, the inhibition of autophagy by promoter methylation of ULK2, which leads to downregulation of transcript levels, was essential for cancer growth under the genetic background of ATG5." (PMID 34901004, 2021). "Mechanistically, genetic or pharmacological inhibition of SRMS induced cancer cell senescence in an ATG5- and ATG7-dependent manner." (PMID 34077419, 2021). "Numerous studies have shown that other ATG genes, including ATG2B, ATG5, ATG9B, ATG12, and ATG16L1, are also associated with human different cancers." (PMID 34443541, 2021). "Several studies have shown that the suppression of ATG5 is connected to benign adenomas and the progression of benign tumors to cancer is ultimately a consequence of a defect in autophagy." (PMID 33926066, 2021). "The NRF1 ChIP-seq data from the ENCODE project confirms the binding of NRF1 to ATG5 and ATG7 promoter regions in 4 different cancer cells (HepG2, K562, SK-N-SH, and HeLa-S3 cell lines)." (PMID 34458153, 2021).
cancer (continued). "Interesting to note, cancer cells that lack the autophagy-related 5 (Atg5) protein show a significant reduction in exosome production." (PMID 34568332, 2021). "Doxorubicin-induced autophagy (Dox) plays a pro-survival role in pancreatic cancer cells; thus, the pharmacological inhibition of autophagy by QC or the silence of ATG5 enhances Dox-induced cancer cell death." (PMID 34575981, 2021). "Loss of ATG5 and ATG7 was found to increase basal and maximal respiration as well as proton leak in cancer cells." (PMID 34885250, 2021). "To further demonstrate that the sensitizing effect of HCQ was independent of autophagy status, we investigated the effect of HCQ after knocking down Atg5 in cancer cells." (PMID 34844627, 2021). "Cisplatin was previously shown to generate autophagy in cancers through activation of Beclin-1 and Atg5, followed by the conversion of LC3-I to LC3-II." (PMID 34321115, 2021). "ATG5 is identified as a critical autophagy gene, contributing to the malignant feature of cancer cells, and its higher expression predicts poor prognosis in patients with early-stage ESCC." (PMID 32974198, 2020). "A number of studies on the ATG genes relevance to human cancers showed that other ATG genes are also oncogenically associated, including ATG2B, ATG5, ATG9B, ATG12 and ATG16L1." (PMID 31969156, 2020). "Collectively, our data argue that the expression of autophagy regulatory proteins, Beclin1 and ATG5, together with inactivation of mTOR, play key roles in mediating at least fifty percent of the anti-cancer actions of [602 + doxorubicin]." (PMID 32983965, 2020). "Specifically, genes such as ATG16L1, ATG5, ATG10 or ATG7, accumulate multiple SNPs linked to pathologies that include cancer, neurological disorders, or inflammatory bowel diseases." (PMID 33147747, 2020). "It was also proved that genetic silencing of Beclin1, Atg5, Atg 7, and Atg12 led to the sensitization of chemoresistant cancer cells to multiple chemotherapeutics." (PMID 32717981, 2020). "Mouse mammary basal-like carcinoma 4T1 cells were used to establish the autophagy-incompetent model, which was generated by the depletion of Atg5 or Beclin1 with specific sgRNAs." (PMID 32732922, 2020). "We thus investigated the impact of ATG5 RNAi on the expression levels of EMT transcription factors in the same panel of cancer cell lines." (PMID 30782064, 2019). "Increased acidity in the TME can lead to the expression of the autophagy regulator autophagy-related 5 (ATG5) in preinvasive cancer cells." (PMID 31906017, 2019). "Cachectic muscle waste and loss have been associated to hypercatabolic breakdown of the muscle by autophagy: LC3B-II, ATG5 and Beclin1 have been shown to accumulate in skeletal muscle tissue from cachectic cancer patients and in cancer mouse models." (PMID 31121959, 2019). "In CRCs with high microsatellite instability, 27% of the cancers harbored at least one mutation in either ATG2B, ATG5, ATG9B, or ATG12." (PMID 31671556, 2019). "We observed that the tissue levels of Atg5 increased gradually from control, dysplasia and cancer in H. pylori-positive group." (PMID 30742638, 2019). "We found that shRNA-mediated knockdown of ATG5 only marginally affects the sensitivity of cancer cells towards PDT." (PMID 29463237, 2018). "To address the role of autophagy in regulating the sensitivity of cancer cells to Photofrin-PDT we downregulated ATG5, a key gene to trigger autophagy, via two different methods: shRNA and CRISPR/Cas9." (PMID 29463237, 2018). "Meanwhile, ATG5 is a key player and its des-regulation is closely related to chemoresistance in a variety of cancers." (PMID 29382381, 2018). "The analysis of multiple cancers showed the overexpression of ATG5 in gastric and prostate cancers while overexpression of ATG7 was seen in bladder cancer." (PMID 29643976, 2018). "We establish a RAS mutant cancer cell model where the autophagy gene ATG5 is dispensable in A549 cells in vitro, yet promotes tumorigenesis in mice." (PMID 29146913, 2017).
cancer (continued). "We designed chitosan nanoparticles (NPs) to promote the co-delivery of gefitinib (an anti-cancer drug) and shRNA-expressing plasmid DNA that targets the Atg-5 gene (shAtg-5) as an autophagy inhibitor to improve anti-cancer effects and autophagy mediation." (PMID 28399862, 2017). "Functionally, by knockdown of essential autophagy genes Atg5 or Beclin1 in bacteria-infected cancer cells, the autophagy pathway was blocked, which led to a significant increase of intracellular bacteria multiplication in cancer cells." (PMID 27013582, 2016). "Inhibition of ER stress-induced autophagy, by knocking down Atg5 in cancer cells, improved the maturation of IL-6 secreting DCs, and thus triggered proliferation of IFNγ-producing CD4+ and CD8+ T cells." (PMID 27917371, 2016). "We demonstrated that ZFE-induced cancer cell death and autophagic vacuolization were clearly suppressed by ATG5 knockdown." (PMID 27626481, 2016). "The hallmarks of autophagy, LC3 and ATG5, were both upregulated in resveratrol-treated cancer cells." (PMID 26067645, 2015). "For instance, miR-181a and miR30a have been reported to inhibit autophagy in cancer cells by down-regulating ATG5." (PMID 26536662, 2015). "It has been clarified that impairment of autophagy system by knocking down Atg5 or Atg7 induces apoptosis of cancer cells, inhibiting cell growth." (PMID 24725767, 2014). "Calpain-mediated the N-terminal cleavage of ATG5 was reported in cancer cell lines undergoing apoptosis and in tubular cells in cisplatin nephrotoxicity models." (PMID 23691217, 2013). "Altered ATG5 expression has been found in various types of cancers, including prostate cancers and gastrointestinal cancer." (PMID 23840208, 2013). "In fact tumor cells overexpressing Atg5 were reported to be more sensitive to chemotherapy, while in case of gene silencing, cancer cells were partially resistant to anti-cancer drugs." (PMID 24710488, 2012). "However, this contradicts studies indicating that, in CRC, inhibition of autophagy via Atg5 knockout enhances cancer cell sensitivity to apoptosis." (PMID 41374004, 2025). "It is speculated that CD46 and TREM1 may inhibit autophagic apoptotic genes LC3B and ATG5 by mediating the activation of the inflammatory cancer chain, thus weakening the apoptotic signal and leading to the proliferation and escape of cancer cells." (PMID 40475017, 2025). "Atg5 promotes the apoptosis of macrophages by enhancing the Fas-FasL signaling pathway after malaria infection, which is mechanically distinct from Atg5-mediated apoptosis of cancer cells." (PMID 40091054, 2025). "ATG5 plays an essential role and is often dysregulated in cancer cells." (PMID 40426890, 2025). "A reduction in ATG5 has also been shown to promote apoptosis in malignant and cancer stem cells." (PMID 38913914, 2024). "In addition, several studies have observed that mutations in ATG2B, ATG4, ATG5, ATG12, and ATG9B are frequently present in human cancer cells." (PMID 38482052, 2024). "In fact, ATG5 has been the center of attention for cancer treatment due to its implication in controlling cell proliferation, migration, invasion and the tumor immune microenvironment, which affects radio- and chemo-therapy resistance, along with the overall patient survival." (PMID 39075259, 2024). "In ICD-suffering cancer cells, upon knocking down Beclin-1, ATG5 or ATG7 could reduce the ATP release and consequently inhibit anticancer immunity in vivo." (PMID 36814780, 2023). "Moreover, knockout experiments of autophagy-related proteins like ATG7, ATG5, and Beclin-1 enhanced the invasiveness of cancer cells in glioblastoma." (PMID 37893079, 2023).